STAT3 (signal transducer and activator of transcription 3)
Diseases named in the same sentence as STAT3 in open-access papers (continued):
Sharing a sentence is not in itself a finding about the gene and the disease.
Thrombocytosis (3 papers, 2010 to 2025). Increased numbers of platelets in the peripheral blood. "IL-6, as a key upstream regulator of JAK/STAT signaling, can activate STAT3 and related downstream molecules, enhance thrombopoietin expression, and drive excessive myeloid proliferation, ultimately leading to secondary (reactive) thrombocytosis." (PMID 41438978, 2025). "The ablation of Stat3 resulted in an altered JAK2 V617F phenotype, with decreased neutrophilia, although thrombocytosis was enhanced, while the ablation of Stat1 actually exacerbated JAK2 V617F-induced erythrocytosis in a mouse model despite reducing the thrombocytosis." (PMID 38254802, 2024).
thymic epithelial tumor (3 papers, 2010 to 2016). "As an indicator with good prognostic value in forecasting recurrence/metastasis, STAT3 may improve the diagnostic accuracy and provide better approaches in clinical practice for thymic epithelial tumor." (PMID 23590999, 2013). "Cox regression analysis revealed that positive expression of STAT3 protein was an independent prognostic factor of thymic epithelial tumors (HR = 9.325, P = 0.044)." (PMID 23590999, 2013). "Positive expression of STAT3 protein increases along with the rising malignant degree of thymic epithelial tumors." (PMID 23590999, 2013). "Expression of STAT3 protein in 80 thymic epithelial tumors was detected by immunohistochemistry (IHC)." (PMID 23590999, 2013). "However, little systematic researches have been reported on the correlation between STAT3 and thymic epithelial tumor (TET)." (PMID 23590999, 2013). "In summary, STAT3 may be used as an independent parameter to evaluate prognosis for patients with thymic epithelial tumor." (PMID 23590999, 2013). "However, few researches have reported on relationship between STAT3 and thymic epithelial tumors." (PMID 23590999, 2013). "Therefore, detection of STAT3 expression level may have vital importance to evaluate the prognosis of TET, especially precise for the highly malignant thymic epithelial tumor." (PMID 23590999, 2013).
undifferentiated pleomorphic sarcoma (3 papers, 2020 to 2024). An undifferentiated soft tissue sarcoma characterized by the presence of a pleomorphic malignant cellular infiltrate. "At the same time, the phosphorylation of STAT3 is significantly associated with the prognosis of undifferentiated pleomorphic sarcoma." (PMID 32780509, 2020).
urinary tract infection (3 papers, 2022 to 2023). "Lin and colleagues recently identified nitroxoline, an antibiotic for the treatment of urinary tract infections, as a new signal transducer and activator of transcription 3 (STAT3) inhibitor." (PMID 36845731, 2023). "Undoubtedly, the involvement of the JAK/STAT pathway in bladder pathologies deserves further investigation, as the deactivation of the IL6/STAT3 signaling has been shown to impair the antimicrobial response in urinary tract infection." (PMID 36982831, 2023).
uterine carcinosarcoma (3 papers, 2019 to 2022). A usually aggressive malignant neoplasm arising from the uterine corpus and less often the cervix. "FOXQ1 also activated the following pathways in uterine carcinosarcoma: the androgen response pathway, IL6/JAK/STAT3 signaling pathway, interferon–alpha response pathway, adipogenesis pathway, and allograft rejection pathway." (PMID 36118871, 2022). "In uterine carcinosarcoma cells, RACGAP1 positively regulated STAT3 phosphorylation and survivin expression, and these activated signaling pathways induced an invasive phenotype." (PMID 30866526, 2019).
Ventricular arrhythmia (3 papers, 2020 to 2025). "Importantly, Ruxolitinib, originally discovered as a JAK inhibitor upstream of STAT3, was recently shown to possess CaMKII inhibitory properties and protect against ventricular arrhythmias." (PMID 40048254, 2025).
actinic keratosis (2 papers, 2011 to 2019). A precancerous lesion of the skin composed of atypical keratinocytes. "Actinic keratosis, a premalignant lesion of SCC, also over-expressed p-Stat3 if the adjacent SCC was also positive for p-Stat3." (PMID 21197106, 2011). "Nuclear STAT3 signal is observed in CSCC and adjacent actinic keratosis, although in non-peritumoral actinic keratosis, STAT3 activation occurs in the plasma membrane and cytoplasm." (PMID 31052530, 2019).
acute aortic dissection (2 papers, 2020 to 2021). "Therefore, lnc-C2orf63-4-1 negatively regulated the expression of STAT3 and prevented the development of aortic dissection." (PMID 34938738, 2021).
acute leukemia (2 papers, 2014 to 2025). A clonal (malignant) hematopoietic disorder with an acute onset, affecting the bone marrow and the peripheral blood. "In the acute leukemia group, CSF3R mutations co-occurred with alterations in signaling pathway genes, including JAK3, STAT3, and NRAS." (PMID 40806796, 2025). "Co-mutations varied by subtype; MDS/MPN, NOS, and CMML cases frequently harbored mutations in epigenetic regulators (ASXL1, TET2) and splicing factors (SF3B1, SRSF2, ZRSR2), while acute leukemia cases showed alterations in JAK3, STAT3, and NRAS." (PMID 40806796, 2025).
acute liver failure (2 papers, 2016 to 2026). Rapid deterioration of liver function causing encephalopathy and coagulopathy. "Collectively, these studies strongly suggest that inactivation of STAT3 represents a critical event in the mechanism of the astrocyte swelling associated with acute liver failure." (PMID 27918421, 2016). "In aggregate, our findings suggest that targeting STAT3 may represent a promising approach for the treatment of the brain edema associated with acute liver failure." (PMID 27918421, 2016).
Alexander disease (2 papers, 2015 to 2023). Alexander disease (AxD) is a rare neurodegenerative disorder of the astrocytes comprised of two clinical forms: AxD Type I and Type II manifesting with various degrees of macrocephaly, spasticity, ataxia and seizures and leading to psychomotor regression and death. "In conclusion, we show that lithium decreases GFAP in a mouse model of Alexander disease, possibly through transcriptional mechanisms involving STAT3." (PMID 26378915, 2015). "Due to its reported effects on autophagy, STAT3, and GFAP, we sought to test whether lithium could decrease GFAP levels in a mouse model of Alexander disease." (PMID 26378915, 2015).
amoebiasis (2 papers, 2021 to 2024). "These proteins were potentially regulated by STAT3 and mainly involved in IL-18 signaling and complement systems, RAS processing and amoebiasis." (PMID 34768771, 2021). "Furthermore, deregulated proteins were mapped in cell–cell contact zones and ciliary basal bodies, potentially regulated by STAT3 and involved in IL-18 signaling and complement systems, RAS processing, and amoebiasis." (PMID 38535507, 2024).
anal carcinoma (2 papers, 2013 to 2017). "However, the specific role of STAT3 in tumorigenesis of human anal cancer is still poorly understood and warrant further investigation." (PMID 28747781, 2017). "Moreover, the animal model shares more biological markers that are similar to other human cancers, such as activation of EGFR and increased levels of p-Stat3 and pro-inflammation cytokines, which could provide more strategies for exploring anal cancer treatments." (PMID 24124460, 2013).
angiosarcoma (2 papers, 2016 to 2018). A malignant tumor arising from the endothelial cells of the blood vessels. "In these models, animals developed angiosarcoma in the lung, liver, and spleen and systemic inhibition of Ikkβ, IL-6 or STAT3 significantly inhibited angiosarcoma growth." (PMID 27105514, 2016). "Phosphorylation of STAT3 has been implicated in the growth of angiosarcoma cells however neither rapamycin nor trametinib treated tumors were found to have consistently elevated levels of phospho-STAT3 Y705." (PMID 29872503, 2018). "However, phospho-STAT3 was not consistently elevated in angiosarcomas relative to endothelial cell controls (data not shown)." (PMID 29872503, 2018).
aristolochic acid nephropathy (2 papers, 2016 to 2021). "IL-6-induced STAT3 activation was observed in mice with HgCl2-induced AKI, and IFN-γ has been shown to activate STAT1 in glomerular mesangial cells in an aristolochic acid nephropathy mouse model." (PMID 33511217, 2021).
Arrhythmia (2 papers, 2018 to 2021). Any cardiac rhythm other than the normal sinus rhythm. "We next tested whether enhanced RISK/SAFE pathway induction was causally linked to the reduced IR susceptibility in female versus male Kcne4−/− mice, by quantifying the effects on post-IR arrhythmia incidence of pharmacological inhibitors of ERK1/2 (U0126), AKT (wortmannin) and STAT3 (Ag490)." (PMID 29844497, 2018).
Arterial thrombosis (2 papers, 2022). The formation of a blood clot inside an artery. "In summary, our data suggest that via inhibiting Mito-STAT3 to elicit Mito-ROS generation, C5a triggers the generation of NETs to promote the development of arterial thrombosis." (PMID 35488279, 2022). "STAT3 is also involved in collagen-induced platelet aggregation and thrombosis and was found to be activated in this study, indicating its role in early arterial thrombosis." (PMID 35645372, 2022).
Ataxia (2 papers, 2016 to 2025). Ataxia refers to impaired coordination of voluntary muscle movement. "Our data show that gp130/Stat3-driven Klf6 induction promotes differentiation, whereas mice with lineage-selective inactivation of Klf6 or upstream Stat3 signaling show profound failure of CNS myelination, which results in tremor, ataxia, and death." (PMID 27213272, 2016).
autism spectrum disorder (2 papers, 2022 to 2024). A spectrum of developmental disorders that includes autism, and Asperger syndrome. "Accumulating evidence highlighted the role played by the JAK2/STAT3 axis and PPAR-gamma signaling in the pathogenesis of autism spectrum disorders." (PMID 39596986, 2024).
B-cell neoplasm (2 papers, 2010 to 2023). A group of heterogeneous lymphoid tumors generally expressing one or more B-cell antigens or representing malignant transformations of B-lymphocytes. "Previous studies demonstrated the critical roles of STAT3 and PI3K in survival, growth, and chemotherapy resistance of plasma-cells and B-cells neoplasms." (PMID 37344563, 2023). "Although activation of NF-κB, STAT3 and/or the PI3K/AKT pathway in B cell neoplasms has been described, the mechanism by which these pathways contribute to the development of BCLs remains unclear, as do the circumstances under which this occurs." (PMID 20433747, 2010). "The finding that NF-κB, STAT3 and PI3K are constitutively activated in LBLs and iMycEμ-1 cells is in keeping with the aberrant activity of these pathways observed in various types of B cell neoplasms." (PMID 20433747, 2010).
Barrett esophagus (2 papers, 2017 to 2021). Esophageal lesion lined with columnar metaplastic epithelium which is flat or villiform. "STAT3 regulates IL-6 genes and expression of STAT3 increases during the transition from Barrett’s metaplasia to adenocarcinoma." (PMID 28757556, 2017).
Behçet’s disease (2 papers, 2021 to 2025). "It is known that JAK1/STAT3 signaling pathway is activated in some systemic vasculitides (Behcet disease) through the activation of Th1/Th17-type cytokines such as IL-2, interferon (IFN-γ), IL-6, IL-17, and IL-23 but its role in KD is not well-understood." (PMID 33692975, 2021). "Additionally, genetic factors may contribute to this regulation, as genetic variants in STAT3, STAT4, and JAK1 have been associated with an increased risk of ocular involvement in patients with Behçet’s disease." (PMID 40270958, 2025).
biliary tract cancer (2 papers, 2020 to 2024). "Finally, an orally administered small molecule STAT3 inhibitor Napabucasin, which is currently being tested in several clinical trials against various cancer models, have been shown to decrease both STAT3 activation and CD44 expression in biliary tract cancer cells." (PMID 33335857, 2020).
bullous pemphigoid (2 papers, 2017 to 2020). Bullous pemphigoid (BP) is the most common form of autoimmune bullous dermatosis. "In our research, the expression of STAT3 in BP skin lesions suggests participation of the protein in pathogenesis of bullous pemphigoid." (PMID 29203970, 2017).
calcinosis (2 papers, 2023 to 2024). Deposition of calcium in the tissues. "Thus, the tofacitinib blocking STAT3 pathway can serve as a therapeutic approach for calcinosis." (PMID 37853451, 2023). "Tofacitinib may improve skin and muscle symptoms and calcinosis in patients with DM through an imbalance in mitochondrial calcium storage and release mediated by the JAK/STAT3/HIF pathway." (PMID 39575238, 2024).
cartilage disease (2 papers, 2022 to 2024). Softening and degeneration of the CARTILAGE. "Researchers found that STAT3 has a fundamental role in regulating DNA methylation in cartilage disease." (PMID 38398778, 2024). "Many other signaling pathways, such as MAPK, NF-κB, NO/cGMP, RANKL, NRF2/HO-1, and JAK/STAT3, have been involved in the network of regulation orchestrated by genistein in protecting against bone and cartilage diseases." (PMID 36160403, 2022).
cataract (2 papers, 2019 to 2025). Partial or complete opacity of the crystalline lens of one or both eyes that decreases visual acuity and eventually results in blindness. "Mechanistically, dual-luciferase experiments revealed that NR2F1 bound directly to the promoter of STAT3 and regulated the expression of p-STAT3, resulting in the development of cataracts." (PMID 40641526, 2025). "Our findings, which stem from both in vitro cell cultures and an injury-induced ASC in vivo model, underscore the indispensable role of the STAT3 pathway in the EMT of human lens epithelial cells and fibrotic cataracts." (PMID 40641526, 2025). "Cytokines IL-6, IL-17 and growth factor VEGF and PDGF are potent activators of STAT3, and the vitreous levels of these cytokines/growth factors were significantly higher in PDR patients compared with those in cataract patients." (PMID 31286987, 2019). "Mechanically, NR2F1 proteins directly interacted with the promoter region of STAT3 and orchestrated the up-regulation of phosphorylated STAT3 (p-STAT3), thereby facilitating the apoptosis and migration of SRA01/04 cells via the JAK1/STAT3 pathway, resulting in epithelium fibrosis and cataracts." (PMID 40641526, 2025).
chronic asthma (2 papers, 2013 to 2021). An asthma that is characterized by the development of persistent airway inflammation and recurrent attacks of breathlessness and wheezing, which vary in severity and frequency. "One investigation showed that airway epithelial STAT3 was responsible for allergic inflammation by modulating Th2 cell recruitment and effector function in a murine model of chronic asthma." (PMID 23737822, 2013).
chronic cystitis (2 papers, 2020 to 2023). Recurrent infections of the urinary bladder. "The RNA seq data showed significant enrichment of the JAK/STAT pathway, whereas the downstream validation of the identified DEGs revealed JAK3 and STAT3 as the key signaling molecules in CYP-induced chronic cystitis." (PMID 36982831, 2023). "Our studied groups showed higher values of CDK4 and STAT3 expression in malignant tissues (SCC andUC collectively) compared to cystitis, however, significantly higher values of CDK4 and STAT3 expression were detected in UC group compared to SCC group." (PMID 32102537, 2020). "Our findings comparing different studied groups showed higher values of STAT3 percent and score of expression in malignant tissues (SCC andUC) compared to cases of cystitis, with statistically significant differences (p<0.001 and p<0.01 respectively)." (PMID 32102537, 2020).
chronic gastritis (2 papers, 2020 to 2022). Inflammation of the stomach that is chronic in nature. "Deoxycholic acid (DCA) is the main bile acid (BA) component of duodenogastric reflux and has shown an increased concentration during the transition from chronic gastritis to IM associated with continued STAT3 activation." (PMID 36067404, 2022).
chronic hepatitis C (2 papers, 2009 to 2020). "In patients with chronic hepatitis C virus infection, M-MDSCs have higher levels of phosphorylated STAT3 and IL-10, while blocking STAT3 signaling reduces hepatitis C virus (HCV)-mediated M-MDSC expansion and IL-10 expression." (PMID 32793192, 2020). "A fourth group reported found reduced STAT3 expression levels in livers of patients with chronic hepatitis C and reported that HCV expression in Huh7 cells inhibited IFN-α induced phosphorylation of STAT1, STAT2 and STAT3." (PMID 21994583, 2009).
chronic lymphoid leukemia (2 papers, 2014 to 2023). "Phosphorylation at Ser727 was previously shown to promote nuclear localization with the transcriptional activity of STAT3 in chronic lymphoid leukemia cells." (PMID 37488242, 2023).
chronic rhinosinusitis (2 papers, 2019 to 2023). Chronic form of sinusitis. "Our results also further validate our proposal that IL-19 up-regulates MUC5AC production in chronic rhinosinusitis via the STAT3 pathway." (PMID 31379870, 2019).
coccidiosis (2 papers, 2022). A parasitic infection caused by Coccidia. "In brief, this study is the first to find circDCLRE1C to be significantly upregulated in chicken coccidiosis, along with dramatically aggravated macrophage inflammation by sponging miR-214b-3p target sites and modulating STAT3 expression, and that circDCLRE1C is an upstream regulator of STAT3." (PMID 35743265, 2022).
diabetic insulin resistance (2 papers, 2019 to 2022). "In insulin-resistant diabetic mice, overexpression of STAT3 not only increases plasma triglyceride and total cholesterol levels but also promotes transcription of lipid synthesis-related enzymes such as fatty acid synthase and acetyl-CoA carboxylase." (PMID 31223625, 2019).
dissection (2 papers, 2020 to 2021). The separation and isolation of tissues for surgical purposes, or for the analysis or study of their structures. "Specifically, we identified that lnc-C2orf63-4-1 affected aortic dissection through mediating the function of signal transducer and activator of transcription 3 (STAT3), which exerted pro-apoptotic effects in VSMCs, leading to subsequent vascular remodeling." (PMID 34938738, 2021).
ductal carcinoma in situ (2 papers, 2021 to 2026). "Furthermore, prophylactic losartan treatment was shown to reduce ductal carcinoma in situ (DCIS) progression and correlated with lower IL-6 and p-STAT3 expression." (PMID 41408463, 2026).
dyskeratosis congenita (2 papers, 2019 to 2025). Dyskeratosis congenita (DC) is a rare ectodermal dysplasia that often presents with the classic triad of nail dysplasia, skin pigmentary changes, and oral leukoplakia associated with a high risk of bone marrow failure (BMF) and cancer. "Twenty (20.41%) had PID: 13 Common Variable Immune Deficiency (CVID), three IgG-2 subclass deficiency, one dyskeratosis congenita, one hyper IgE syndrome (STAT3 dominant negative loss of function deficiency) and one patient with interferon-γ receptor and interleukin-12 deficiency, one patient each." (PMID 31801528, 2019).
eating disorder (2 papers, 2022 to 2024). A broad group of psychological disorders with abnormal eating behaviors leading to physiological effects from overeating or insufficient food intake. "Changes in CpG methylation levels in individuals with AN compared to healthy controls could affect expression of the STAT3 gene and therefore the leptin signaling pathway, leading to impaired regulation of appetite and energy balance and thus to metabolic or eating disorders." (PMID 38849516, 2024). "Moreover, the malfunction of signaling molecules in the CCK/SRC/PI3K cascade reaction with leptin/JAK2/PI3K/STAT3 signaling pathway may lead to eating disorders." (PMID 36359184, 2022).